IL6 (interleukin 6)
Diseases named in the same sentence as IL6 in open-access papers (continued):
Sharing a sentence is not in itself a finding about the gene and the disease.
viral infection (continued). "The effects of Aβ pathology on the viral infection of SARS-CoV-2 and the induction of IL-6 in host cells involve close interactions between Aβ1-42 and the S1 of SARS-CoV-2 and ACE2." (PMID 34360989, 2021). "Notably, HIF-1α, IL-1β, IL-6, and IFN-β mRNAs and HIF-1α protein were induced in infected cells, suggesting that HIF-1α and immune and inflammatory cytokines are induced upon the virus infection, and HIF-1α expression is linked to immune-inflammatory cytokine expression in infected cultured cells." (PMID 34408131, 2021). "Consistently, it was reported that not only interferon treatment or viral infection increased ACE2 levels, several inflammatory cytokines stimulation, such as TNFα, IL6 and IL1β, also increased the level of ACE2." (PMID 34867400, 2021). "Remarkably, A5+ also reduced production of IL-6 in cells infected with IAV, suggesting its potential effect in the reduction of inflammation and immune mediators after viral infection with different IAV viruses, such as the virus A/PR/8/H1N1." (PMID 34829949, 2021). "Induction of proinflammatory cytokines such as IL-1β, IL-6, IFN-α, and TNF-α, is indicative of acute viral infection in animals." (PMID 31906555, 2020). "PCT synthesis is stimulated by cytokines such as IL-6, IL-1β, and TNF-α, or directly by lipopolysaccharides and it is downregulated by interferon-γ, which is commonly produced in response to viral infections." (PMID 33419284, 2020). "Serum ferritin levels are particularly elevated in various viral infections, partly to extreme ranges of more than 1000 μg/L, while CRP and IL-6 values are often only mildly elevated." (PMID 32707842, 2020). "IRF upregulation induced by Type I and II Interferons, viral infection, LPS in addition to several cytokines including TNF-a, IL-1β, IL6 and IL23." (PMID 33137133, 2020). "Viral infection increased the released of pro-tumorigenic cytokines including the immune suppressive IL-10 and VEGF and the pro-inflammatory cytokines IL-6 and IL-8." (PMID 32418990, 2020). "First, Type II alveolar cells will secrete a host of inflammatory cytokines in response to viral infection such as IL-1β, IL-6, TNF-α, CXCL10, and CCL2 that will act to recruit other inflammatory cells to help abate the viral infection." (PMID 32760409, 2020). "The components of this minimal gene signature related to IL-6 include DHX58, IFIH1, ISG15, and PNPT1, which it shares with the gene signature observed after yellow fever vaccination." (PMID 33244316, 2020). "The combined detection of IL-6, PCT, and CRP can provide a differential diagnosis of early bacterial and viral infections." (PMID 32851063, 2020). "After virus infection, the levels of IFN-β, TNF-α and IL-6 were markedly increased compared with the control uninfected group (P < 0.01 or P < 0.05)." (PMID 31551774, 2019). "Viral infection activates PRRs and leads to the transcription of ISGs (e.g., Mx and OAS) and pro-inflammatory cytokines (e.g., IL-6 and IL-8)." (PMID 31428075, 2019). "In a previous study on the role of CARD9 in proinflammatory cytokine production during viral infections, in vitro stimulation of CARD9−/− DCs with influenza A virus (IAV) also showed an impaired IL-6 and TNF-α production." (PMID 30917612, 2019). "The mRNA expression levels of IL-1β, IL-6, IL-8, IFNs, TNF-α, Mx, and OASL were significantly upregulated during the viral infection." (PMID 31288442, 2019). "Mice infected with a mixture of rgH5N1 virus and F.G.B displayed lower levels of inflammatory cytokines (IL-6, TNF-α) in lung and in BALF compared to virus infection of the control mice." (PMID 30200514, 2018). "STAT1 is an important transcription factor to promote IL-6-dependent Bcl6 induction and TFH differentiation during the DC priming stage of acute viral infections." (PMID 30057920, 2018). "Meanwhile, B4GALT5 up-regulated the expression of IFN-α and inflammatory factors (IL6, IL-18, IL-1β, TNF-α) to resist viral infection." (PMID 29546034, 2018).
viral infection (continued). "Synergistic effects of IL-1β, IL-6 and TNF-α on inflammatory and stress mediators and IL-1β and IL-17 on chronic lung inflammation after viral infection have been reported." (PMID 27714503, 2017). "At day 2 postinfection, both TNF-α and IL-6 transcripts were moderately induced by wild-type virus, while CCL2, CCL4, CXCL9, and CXCL10 mRNA levels were all highly elevated by wild-type virus infection." (PMID 29138302, 2017). "Because virus infection can lead to the production of the pro-inflammatory cytokines IFN-γ, TNF-α, IL-1ß, and IL-6, which contribute to inflammation, the expressions of these cytokines were measured." (PMID 28417913, 2017). "In dendritic cells of patients with COPD, OM-85 increased the secretion of IL-1α, IL-1β, IL-6 and TNF-α, which was regarded as a strengthening of the immune response during viral infection." (PMID 29182620, 2017). "IL-6 affects differentiation of CD4 T cells and can also modulate aspects of the innate immune response to viral infection." (PMID 28746373, 2017). "For instance, RIPK1 was shown to be essential in inducing inflammatory cytokines (IL-6, IL-1β, TNF-α) in response to bacterial and viral infections." (PMID 28410401, 2017). "IL-10 down-regulates the immune response after virus infection by inhibiting IFN-γ production, antigen presentation, and macrophage production of IL-1, IL-6, and TNF-α." (PMID 28086978, 2017). "Levels of twelve cytokines and chemokines in the apical supernatant of hAECs were elevated following A(H7N9) virus infection, including GRO-α, MIP1-α, MIP1-β, SDF-1α, RANTES, IL-1α, IP10, IL-1RA, MCP1, IL-8, IL-6, and IL-1β." (PMID 28900138, 2017). "The levels of either gene expression or cytokine proteins (IL-1α, TNFα, IL-6, CXCL10, CCL5, CCL2, CCL3, CCL4, and CCL5) in RSV-infected PMФ are comparable to the H5N3 virus infection." (PMID 28558796, 2017). "The serum of FAF1gt/gt mice contained more replicating virus and lower levels of IFN-β and IL-6 than that of FAF1+/+ mice, indicating that knockdown of FAF1 suppresses cytokine secretion upon virus infection." (PMID 28542569, 2017). "Although Vsig4 deficiency did not seem to affect the basal expression level of these factors before viral infection, qRT-PCR data showed that MHV-3 infection super-induced Vsig4−/− PEMs to express Fgl2, Tnf, Il-1β, and Il-6." (PMID 29109438, 2017). "We observed increased level of inflammatory mediators (IL-1α, IL-1β, IL-6, MIP-1α (CCL3), MIP-1β (CCL4), RANTES (CCL5), MCP-1 (CCL2)) following H5N3 virus infection at 4, 8 and 20 hpi compared to cells infected with the H1N1/WSN, H5N2 and H9N2 viruses." (PMID 28558796, 2017). "In our study, levels of 12 cytokines and chemokines in the apical supernatant of hAECs were elevated following A(H7N9) virus infection, including GRO-α, MIP1-α, MIP1-β, SDF-1α, RANTES, IL-1α, IP10, IL-1RA, MCP1, IL-8, IL-6, and IL-1β." (PMID 28900138, 2017). "Increased expression of IL6 and CASP1 is known to be involved in the cellular response to viral infection." (PMID 26871479, 2016). "IL-6R signalingactivates the transcription factor STAT1 specifically in CD4+ T cells.Furthermore, IL-6-mediated STAT3 activation is important for downregulation of IL-2Rα,which contributes to limit Th1 cell differentiation in an acute viral infection." (PMID 27096200, 2016). "It has been shown that circulating concentrations of both IL-6 and CRP are markedly higher in patients with community-acquired bacterial infections as compared to patients with viral infections." (PMID 27977798, 2016). "Oncolytic herpes simplex virus–resistant Ewing sarcoma tumors that express IL-1β, IL-6, and CXCL1 induce CD11b+ cell expression of VEGF after virus infection." (PMID 28536380, 2016). "During viral infection or pI:C transfection of mouse embryonic fibroblasts, IFN-β and IL6 escape translational blockade, which is dependent on the eIF2α phosphatase GADD34." (PMID 27941826, 2016).
viral infection (continued). "The data demonstrated that when cells were pretreated with SB203580, cytokines such as IL-6, IL-8, and TNF-α significantly decreased following virus infection." (PMID 26008703, 2015). "Meanwhile, the slight changes observed in IL-6 and CRP levels exclude bacterial infection, thereby indicating a high probability of viral infection." (PMID 25996387, 2015). "Virus infection in cardiac myocytes initiated the expression of pro-inflammatory cytokines including TNF-α, IL-6, IL-1β and chemokines." (PMID 25728713, 2015). "High levels of IL-6 and MCP-1 were also found in spinal cord and brain indicating that viral infection had induced intense inflammatory response in CNS." (PMID 25993659, 2015). "After viral infection, KIOM-C-treated RAW264.7 cells induce levels of secreted IL-6 and IFN-β like LPS-treated cells." (PMID 25942440, 2015). "As our data show, the induction of IL-6, RANTES, IP-10, and MIP-3α, responsive to the viral infection, was significantly suppressed in the presence of the inhibitor, indicating that these proinflammatory cytokine or chemokine inductions are NFκB-dependent." (PMID 26134299, 2015). "Several pro-inflammatory cytokines (e.g. IL-1, IL-6, TNF-α, and IFN-β, etc) are induced by oxidant stress, cytokines, and virus infection, which play a role in host cell damage, chronic inflammation, and other immunoresponses." (PMID 25548009, 2014). "The levels of IL-6 and KC were significantly higher in WT than in C5ar1−/− mice infected with IAV alone on Day 8 post viral infection." (PMID 24740152, 2014). "Due to viral infection, the expression of TNF-α, IL-6, MCP-1, and IFN-β was significantly increased in cardiac fibroblasts compared to cardiomyocytes or macrophages." (PMID 25374444, 2014). "Duck cells treated with S3I-201 that inhibits the transcriptional activity of STAT-3, resulted in increased expression of LITAF, IL-6 and IL-8 compared with control cells at 24 h post H5N1-tyEng91 virus infection." (PMID 25431115, 2014). "In duck cells treated with S3I-201, a significant (p < 0.05) increase of LITAF, IL-6 and IL-8 mRNA expression was observed at 24 h post H5N1-tyEng91 virus infection." (PMID 25431115, 2014). "Chicken cells over-expressing constitutively active STAT-3 showed significantly lower LITAF, IL-6 and IL-8 mRNA levels compared with the blank plasmid transfected cells at 24 h post H5N1-tyEng91 virus infection." (PMID 25431115, 2014). "Macrophages play important roles in immune responses against various microbial and viral infections by the secretion of nitric oxide (NO) and pro-inflammatory cytokines such as tumor necrosis factor-α (TNF-α), and interleukin-6 (IL-6)." (PMID 25387351, 2014). "Chicken cells transiently transfected with phospho-STAT-3 showed a significant (p < 0.05) reduction in LITAF, IL-6 and IL-8 mRNA expression following 24 h of H5N1-tyEng91 virus infection." (PMID 25431115, 2014). "The concentrations of IL-1Ra, IL-2, IL-6, and TNF-α were significantly higher with the sera from the patients with bacterial infections than the sera from the patients with viral infections or the controls." (PMID 23690657, 2013). "Among the pro-inflammatory mediators, a significant increase in mRNA for CSF2, CSF3, CXCL2, CXCL5, IL6, IL8, and also IL1 and IL18 was observed 24 h after viral infection." (PMID 23723976, 2013). "Pro-inflammatory cytokines, such as IL-1, IL-6, IFN-γ, and TNF-α, are among the first cytokines produced by alveolar macrophages in response to viral infections." (PMID 23631691, 2013). "A curious observation was the inverse correlation of the expression levels of the transcripts of IL-6, TNF-α, CXCL9, CCL2 and CCL3 and the virus infection dose." (PMID 24086645, 2013). "Bacterial etiology of infection was associated with significantly (P < 0.001) elevated serum concentrations of IL-1Ra, IL-2, IL-6, and TNF-α in comparison to levels observed in the sera of patients with viral infections." (PMID 23690657, 2013).
viral infection (continued). "Intestinal mast cells play a central role in innate immune response to bacterial, parasitic, and viral infections by releasing pro-inflammatory cytokines (TNF, IL-6, LTB4) that mediate neutrophil recruitment into infected tissues and bacterial clearance." (PMID 23637741, 2013). "Chemokines and cytokines such as IL-8, IL-6 and regulated on activation, normal T-cell expressed and secreted (RANTES) have been detected during virus infections in asthmatic patients." (PMID 22420941, 2012). "Our data indicate that the induction of IL-6, IL-8, IL-10, CCL-5, as well as IFN-β, were apparent at the earliest stages of viral infection even before ERK1/2 was further activated." (PMID 22279582, 2012). "Growth kinetics and induction of select immune response genes, including IFN-α and myxovirus-resistance gene I (Mx), as well as proinflammatory cytokines (IL-1β and IL-6), were measured in response to chicken IFN-α and viral infection over time." (PMID 21939525, 2011). "Beginning with a low dose (1 × 106 CFU) of heat killed pneumococcal stimulation after virus infection, MoDCs produced significantly lower amount of TNF-α and IL-6 than that treated with pneumococcus alone." (PMID 21771345, 2011). "For instance, with a low dose of pneumococcus, the preceding virus infection appeared to be determinative in skewing the MoDC cytokine production towards suppression of TNF-α, IL-6 and IL-10 as stimulated by the bacteria." (PMID 21771345, 2011). "The activation of mononuclear system cells occurs due to a hypersecretion of proinflammatory cytokines (IFNγ, TNFα, IL6, IL10, M-CSF), as a consequence of a triggering agent, which is often a viral infection." (PMID 18834507, 2008). "The activation of this factor during early stages of viral infection leads to the expression of several immune response genes; such as pro-inflammatory cytokines (IFN-β, TNF-α, IL-6, IL-8), chemokines (RANTES) and adhesion molecules (ICAM-1, VCAM-1)." (PMID 17971236, 2007). "However, in the serum of SARS-CoV-2–infected macaques, we found a transient virus infection–related increase in 2 interferon-γ–driven inflammatory cytokines, CXCL10 and CXCL11, and an increase of CCL2, whereas interleukin-6 was elevated in only 1 animal." (PMID 40876955, 2026). "In addition, we documented that during a viral infection, cytotoxic T-cell (CTL)-secreted IFNy stimulates IL-6 production by MSCs that expands myeloid progenitors." (PMID 40384929, 2025). "Inflammatory markers such as IL-6, PCT, and CRP were markedly higher in bacterial sepsis at ICU admission, consistent with prior studies demonstrating a more robust cytokine response in bacterial versus viral infections." (PMID 40733612, 2025). "IL-2, IL-6, IL-17A, and IFN-γ are common immune factors in viral infections." (PMID 40872344, 2025). "Further, analysis of IL6 and CXCL8 expression corroborated a lack of active viral infection, as IL6 and CXCL8 are upregulated during acute infection." (PMID 41152229, 2025). "The effect of the KerraTM and KSTM treatments upregulating IL6 and STAT3 may indicate their role in enhancing immunity to prevent or clear viral infection." (PMID 40733507, 2025). "STAT3 can be activated by IL-6 and interferon-gamma (IFN-γ) by viral infection." (PMID 40006981, 2025). "The pathogenesis of CD is unknown and probably related to viral infections, such as human immunodeficiency virus, human herpesvirus 8 (HHV-8), and interleukin 6 (IL-6) overexpression." (PMID 40917835, 2025). "Using levels of IL-6, LIGHT, and MMP-2, we differentiated viral infections correctly 95% of the time and CAP infection 54% of the time, yielding an overall accuracy of classification of 83%, a positive predictive power of 81.25%, and a negative predictive power of 83.33%." (PMID 41488910, 2025). "Since CRP directly contributes to antibacterial, but not antiviral, defence, IFNα-dependent suppression of IL6-dependent CRP induction has resource-saving effects in the context of viral infections." (PMID 40632603, 2025).
viral infection (continued). "The serum post-infection evolution of CRP and IL-6 levels showed no significant variation between clusters, which is consistent with the nonspecific response to viral infection or immune challenges in general." (PMID 40076968, 2025). "In the pathogenesis of viral infections, metabolic responses such as decreased insulin sensitivity, increased hepatic gluconeogenesis, and accelerated lipolysis are involved under the influence of proinflammatory cytokines (e.g., TNF-α, IL-6)." (PMID 41150364, 2025). "IL-6 is a pro-inflammatory cytokine that is involved in the non-specific protection of the body against bacterial and viral infections." (PMID 39937802, 2025). "In particular, infections with Punta Toro virus (PTV), influenza A, and vaccinia all led to significant increases in interleukin-6 (IL-6) in WT mice both systemically and at the infected tissues, suggesting the cytokine as a key regulator of TLR3-induced pathogenesis in viral infections." (PMID 39988665, 2025). "By contrast, IL-6 transcription, which was upregulated in response to virus infection but is not regulated by IFN, remained unaffected by ruxolitinib treatment, as expected." (PMID 39937571, 2025). "The resulting network revealed a highly interconnected core centered around key cytokines—including IL-6, IL-1β, IL-10, TNF-α, IL-18, and GM-CSF—which function as pivotal hubs driving the host inflammatory response and immunopathogenesis in both viral infections." (PMID 41366310, 2025). "Pro-inflammatory cytokines (IL-6, TNF-α) are released by neutrophils and macrophages in response to bacterial infections.Interferons and cytotoxic reactions are brought on by viral infections.Immune exhaustion is brought on by persistent illnesses, such as HIV." (PMID 40364844, 2025). "For example, exopolysaccharides of Streptococcus thermophilus ST538 induced the expression of IL6 and CCL2 in porcine intestinal epitheliocytes which could aid against a virus infections." (PMID 39712028, 2024). "Additionally, metformin enhances the production of interferons and other cytokines, such as interleukin-6 (IL-6) and tumor necrosis factor-alpha (TNF-α), which play essential roles in the innate immune response to viral infection and chronic diseases." (PMID 39772244, 2024). "The levels of IL-6, IFNγ, IP-10, were significantly decreased at day 4 after viral infection, but not affected by Apta-1 treatment." (PMID 38474386, 2024). "Given the importance of IL-6, TNF-α, IL-12p40, IL-23, and IL-27 in aiding the immune system during viral infection and supporting viral immunity, a fermentate that can enhance these cytokines could indeed be beneficial." (PMID 39123583, 2024). "Indeed, cytokines such as IL-1β, IL-6 and TNF were shown to be produced in the brain itself following peripheral viral infection, most notably by microglia." (PMID 39107476, 2024). "Although there were individual variations, expression of neuropathic cytokines such as TNF-α, MCP-1, and IL-6 was observed in the brains infected with the Large virus, whereas almost no cytokine detection occurred in cases of Small virus infection." (PMID 39081248, 2024). "Furthermore, 3,5,8-TMON inhibited IL-6 production at concentrations of 12.5 and 3.12 μg mL−1 in Calu-3 cells during SARS-CoV-2 viral infection." (PMID 38390504, 2024). "Regarding T-cell exhaustion in viral infections such as CMV and SARS-CoV-2, it seems that, besides leukopenia, higher IL-6 levels may also affect T-cell exhaustion and secretion of IL-17 by Th17 cells." (PMID 36765433, 2023). "Even though CLEC2.Fc was unable to inhibit virus infection and replication, CLEC2.Fc inhibited the expression of IL‐6, CXCL2, CXCL5, CCL2, and IP‐10 at day 3 and day 5 post‐infection, and the expression of TNF‐α, IFN‐γ, IL‐10, and CXCL1 was also suppressed at day 5 post‐infection (red columns)." (PMID 37211986, 2023).